GLS (glutaminase)
Diseases named in the same sentence as GLS in open-access papers (continued):
Sharing a sentence is not in itself a finding about the gene and the disease.
cancer (continued). "In other cases, cancer cells rely on extracellular glutamine, which enters mitochondrial metabolism via conversion to glutamate through glutaminase (GLS) followed to 2-oxoglutarate production by glutamate dehydrogenase or aminotransferase." (PMID 29463059, 2018). "GLS, especially GLS1, is commonly considered as not only a biomarker of glutamine dependence but also a therapeutic target for many types of cancer." (PMID 29789716, 2018). "Cancer cells rapidly convert glutamine to glutamate due to the high expression of mitochondrial glutaminase (GLS)." (PMID 29632647, 2018). "Other studies have also identified a role of SLC7A11 in regulating glutamine dependency or sensitivity to glutaminase inhibition in cancer cells." (PMID 29764521, 2018). "Glutamine starvation by glutaminase inhibitior, transporter inhibitor, or glutamine depletion has shown to have significant anti-cancer effect in pre-clinical studies." (PMID 28750681, 2017). "In cancer cells, glutaminase is an attractive therapeutic target to regulate proliferation and oncogenic transformation." (PMID 28439409, 2017). "Though pleiotropic roles of glutamine plays in cancer metabolism, it must be firstly deamidized to glutamate by GLS, a prerequisite for the entry of TCA cycle." (PMID 27902968, 2017). "Others found that larger vesicles (microvesicles) are sensitive to glutamine inhibition, as the introduction of a glutaminase inhibitor significantly disrupted their production in cancer cells." (PMID 28427419, 2017). "Here we use a small molecule inhibitor of glutaminase, CB-839, which is currently in clinical phase I trials for multiple cancer types, including LUAD." (PMID 28967864, 2017). "The glutaminase activity in L-asparaginase is believed to exert anti-cancer effect on ASNS-expressing cells." (PMID 28750681, 2017). "Collectively, these experiments suggest that glutaminase dependence in culture for many cancer cells derived from various tumor types will be strongly influenced by both environmental cystine and xCT/SLC7A11 expression." (PMID 28826492, 2017). "Inhibitors of glutaminase activity have gained attention in the last few years due to their anti-proliferative effect and ability to induce apoptosis in some cancers." (PMID 29212209, 2017). "Tremendous effort has been put on glutamine starvation approach by targeting different parts of the glutamine metabolism, that led to the development of specific glutaminase inhibitor CB-839 in clinical trials of different cancers." (PMID 28750681, 2017). "This has led to interest in targeting glutaminase activity therapeutically, and the glutaminase inhibitor CB-839 is being evaluated in clinical trials to treat cancer." (PMID 28826492, 2017). "The current development of drug targeting on glutamine metabolism of cancer cells focuses on glutamine depletion, glutaminase inhibition, and membrane glutamine transporter inhibition." (PMID 28750681, 2017). "As a metabolic enzyme, glutaminase is known to promote cancer cell proliferation and transformation." (PMID 28439409, 2017). "The glutaminase inhibitor BPTES significantly sensitized cancer cells to both MMS and the clinical alkylating agent lomustine (CCNU), confirming that the combination works on a broad range of alkylating agents and across a broad range of cancers." (PMID 29107960, 2017). "This study provides a critical molecular basis to combine glutaminase inhibitors with alkylating agents for more effective treatment of cancers." (PMID 29107960, 2017). "Recent efforts have focused on targeting glutaminolysis by inhibiting the GLS activity in cancer cells." (PMID 29212209, 2017). "As glutaminolysis is crucial for cancer cell proliferation, we next examined the activity of 968 in inhibition of glutaminase in HCC cells." (PMID 27835669, 2016). "Several glutaminase inhibitors were designed and synthesized for targeting glutamine metabolism in cancer therapy." (PMID 26575584, 2016).
cancer (continued). "Glutaminase is a pivotal enzyme in the regulation of glutamine metabolism in tumor cells which has recently gathered some attention as a promising target for cancer therapy." (PMID 28040803, 2016). "Because shGLS1 and GLS inhibitors reduce growth in several types of cancer cell xenografts, we examined the in vivo effects of shGLS1 on tumor growth and metastasis." (PMID 26771232, 2016). "For glutamine metabolism, GLS is the key enzyme in the conversion of glutamine to glutamate and is expressed in many tissue cells and cancer cells." (PMID 26575584, 2016). "Cancer cells have previously been shown to be addicted to glutamine and glutaminase enzyme activity." (PMID 27089238, 2016). "Another compound, Bis-2-(5-phenylacetamido-1, 2, 4-thiadiazol-2-yl) ethyl sulphide, also exhibited inhibitory effects on glutaminase, thus repressing glutamine availability to the cancer cells." (PMID 27825361, 2016). "One of the two GLS isoenzymes, GLS1 is highly expressed in cancer and encodes two different isoforms: kidney (KGA) and glutaminase C (GAC)." (PMID 27806325, 2016). "Our results support asparagine as an important contributor to cancer cell growth and suggest strategies for improving efficacy of asparaginase and GLS inhibitors as cancer treatments." (PMID 27126896, 2016). "They found that the level of glutaminase in the cancer cells was much higher compared to the normal ductal cells." (PMID 27825361, 2016). "Glutaminase is also reportedly upregulated in response to oncogenes such as c-Myc, Raf, Ras and the Rho GTPase and, because of this, glutaminase is an emerging target for cancer therapeutics." (PMID 27462863, 2016). "Glutaminolysis and glutaminase (GLS) have been showed to be indispensable for cancer development and progression." (PMID 26575584, 2016). "Cancer cells obtain glutamine from the blood and use an enzyme called glutaminase to convert it into another type of molecule." (PMID 26751560, 2016). "NDRG2 inhibited glucose transporter 1, and three key regulatory enzymes HK2, PKM2 and LDHA in glycolysis, NDRG2 also inhibited glutamine transporter ASCT2 and glutaminase GLS1 in glutaminolysis, along with the inhibition of c-Myc in cancer cells." (PMID 26317652, 2015). "BPTES, an allosteric inhibitor of glutaminase, was found to preferentially slow the growth of cancer cells expressing mutant IDH1 compared with those expressing WT IDH1." (PMID 25980580, 2015). "The GLS1 gene, located in chromosome 2, encodes two isoforms, kidney-type glutaminase (KGA, long transcript isoform) and the glutaminase C (GAC, short transcript isoform), which are expressed in kidneys and in a variety of other tissues including cancer cells." (PMID 25844758, 2015). "Due to the enhanced glutamine metabolism in most cancers, GLS is being explored as a significant agent in therapeutic interventions." (PMID 26402672, 2015). "Simultaneous inhibition of GLS1 by 968 and tissue transglutaminase by inhibitor e.g., monodansylca-daverine, result in a synthetic lethality across a panel of assorted cancer cell lines." (PMID 26402672, 2015). "As the first critical enzyme for glutamine metabolism, GLS (glutaminase) has been reported to be positively correlated with malignancy in cancers and with growth rate in normal cells." (PMID 26402672, 2015). "Recent work on inhibitors that target glutaminase, the enzyme that catalyzes the conversion of l-glutamine to l-glutamate and ammonia, suggests significant therapeutic potential for cancer treatment." (PMID 26139106, 2015). "The activity of glutaminase (GLS), the first enzyme in glutaminolysis, and glutamine level in the medium correlate with cancer cell proliferation." (PMID 26045471, 2015). "Based on the totality of published data on the importance of Gln and glutaminase in cancer, GLS has been highlighted as a potential drug target for oncology indications." (PMID 25502225, 2014).
cancer (continued). "Herein, we report that natural product alkyl benzoquinones are novel inhibitors of the emerging cancer drug target glutaminase, a discovery made by screening a small collection of natural products." (PMID 25026281, 2014). "Based on the noticeable effects of glutaminase expression levels on the prognosis of cancer patients, we found that competing activities of Gln catabolism and Gln anabolism act as potential biomarkers for predicting patient survival." (PMID 24799285, 2014). "On the contrary, GLS gene has been demonstrated to be regulated by c-Myc oncogene and upregulated in parallel with cancer cell proliferation." (PMID 24096582, 2014). "Recent work has highlighted glutaminase (GLS) as a key player in cancer cell metabolism, providing glutamine-derived carbon and nitrogen to pathways that support proliferation." (PMID 25502225, 2014). "In our study, the relative inhibitory activities of the alkyl benzoquinones of glutaminase were generally consistent with their respective activities for anti-cancer cell growth." (PMID 25026281, 2014). "It is known to stimulate increased expression of its target proteins and glutaminase expression by transcriptional repression of mir23a/b in cancer cells." (PMID 25299066, 2014). "Glutaminase (GLS) was shown to be up-regulated in MYC induction cancer cells and inhibition of GLS decreased the cancer cell growth." (PMID 23590835, 2013). "Glutaminase C is a key metabolic enzyme, which is unregulated in many cancer systems and believed to play a central role in the Warburg effect, whereby cancer cells undergo changes to an altered metabolic profile." (PMID 24098668, 2013). "Dependence of cancer cells on exogenous Gln is driven by Myc protein, which suppresses miR-23a and miR-23b, leading to the induction of glutaminase (GLS)." (PMID 22570721, 2012). "Glutaminase is expressed in most mammalian tissues and cancer cells, but the regulation of its expression is poorly understood." (PMID 22679499, 2012). "Our recent work suggests that the glutamine addiction of cancer cells is enabled by the activation of glutaminase, which catalyzes one of the key steps in glutamine metabolism, as an outcome of post-translational modifications." (PMID 21234284, 2010). "In particular, we would like to obtain structural information that sheds some light on how glutaminase is activated in transformed/cancer cells." (PMID 21234284, 2010). "While the increases in basal glutaminase activity in transformed/cancer cells are dependent on NFκB activity, we know that this is not the result of a direct effect of this transcription factor on glutaminase expression." (PMID 21234284, 2010). "Recently, we have found that this is achieved through a marked elevation of glutaminase activity in cancer cells." (PMID 21234284, 2010). "Given the selective vulnerability of MTAP-deficient cancer cells to CB-839 treatment and the immunoregulatory role of CXCL10, we next evaluated whether glutaminase inhibition could enhance CXCL10 expression." (PMID 41246302, 2025). "Targeting glutaminase in these cancers has been a popular target of therapeutic intervention." (PMID 40568130, 2025). "For example, glutamine anaplerosis and glutaminase dependence in cultured cancer cells is, in part, due to limited cystine availability in standard cell culture media, and also explains why the same cells rely less on glutamine catabolism to proliferate in vivo." (PMID 40473840, 2025). "This aids in developing glutaminase as a therapeutic anticancer enzyme for treatment of cancer." (PMID 40121594, 2025). "Moreover, GLS inhibition impairs the metabolic adaptability of cancer cell, potentially triggering excessive autophagy, resulting in apoptosis." (PMID 41179661, 2025). "This indicates that CB-839 is indeed a potent disruptor of glutaminase in cancer cells." (PMID 41450919, 2025).
cancer (continued). "It seems clear that GLS2 possesses specific functions differentiating it from GLS, and unravelling them may shed light on both its roles in physiological conditions and its impact on cancer." (PMID 39796278, 2025). "Studies have shown that GLS is overexpressed in many malignant tumours." (PMID 41050056, 2025). "The expression of multiple genes in glycolysis and pyruvate metabolism were increased, possibly suggesting that rod PRs are stimulating glucose oxidation to maintain the TCA cycle and mitochondrial function similar to that seen in certain cancer cells when GLS is inhibited." (PMID 40396212, 2025). "An example of cancer cells overcoming antimetabolic therapy and continuing proliferation is the survival of breast cancer cell lines after the administration of GLS inhibitors (BPTES and CB-839), where the cells utilize pyruvate as an alternative anaplerotic substrate." (PMID 40076506, 2025). "Furthermore, the expression of the enzyme glutaminase 1 (GLS1), which is responsible for the deamidation of glutamine to glutamate, is upregulated in many cancer cell lines and correlates with decreased survival in patients." (PMID 41235226, 2025). "Additionally, the discovery of glutaminase inhibitors and other metabolic modulators has opened new avenues for therapeutic intervention, particularly in targeting the vulnerabilities of cancer cells’ reliance on glutamine." (PMID 40567251, 2025). "By inhibiting a broad range of glutamine‐dependent enzymes, including GLS and amidotransferases, they suppress oxidative and glycolytic metabolism in cancer cells, ultimately reducing hypoxia, acidosis, and nutrient depletion, creating a more favorable environment for CD8+ T‐cell function." (PMID 40552664, 2025). "To investigate the role of GLS in cancer, we studied several GLS inhibitors." (PMID 40598593, 2025). "GLS inhibition prevents the conversion of glutamine to glutamate in cancer cells." (PMID 41179661, 2025). "Indeed, inhibition of glutaminase through specific inhibitors is sought to prevent aberrant cell proliferation and sensitize cancer cells to anticancer treatment." (PMID 40114244, 2025). "On the other hand, several studies have shown that GLS is upregulated in different types of cancer." (PMID 38542254, 2024). "Hence, the present review highlights the plausible role of glutaminase in cancer and the current therapeutic approaches and clinical trials to target and inhibit glutaminase enzymes for better cancer treatment." (PMID 38939098, 2024). "Thus far, very little is known regarding how glutaminase activity is activated either in cancer or virus-infected cells." (PMID 39662828, 2024). "However, a previous study reported that targeting glutamine metabolism by a GLS inhibitor alone is insufficient for cancer therapy." (PMID 38386265, 2024). "We tracked tumor formation and progression in WT and GLSKO models before and after treatment with AZD0095 and found that, once lactate uptake was inhibited by AZD0095, the trajectory of tumorigenesis was diminished, specifically in tumors arising from deletion of GLS in cancer cells of origin." (PMID 39303037, 2024). "Thus, the upregulation of GLS isozymes has been correlated with proliferating stages and malignancy in many types of cancer and experimental tumors." (PMID 38542254, 2024). "Multiple studies have indicated that the overexpression of GLS observed in many cancers may not only decrease glutamine levels but also elevate intratumoral glutamate levels." (PMID 38459595, 2024). "Moreover, delving into the metabolic needs of cancer cells, such as using glutaminase inhibitors, presents an intriguing avenue in research." (PMID 39064229, 2024). "In addition, polyfactorial processes (glutamine transporters, glutaminase and aminotransferase) are involved in GM in various cancers." (PMID 38506093, 2024). "Cancer cells may be more sensitive to glutaminase inhibition under high glutamine import compared with that under low glutamine import." (PMID 37842240, 2023).
cancer (continued). "The differences in term of Pi transporters and glutaminase levels between these two cancer cell lines may also reflect a different sensitivity to treatments." (PMID 37627630, 2023). "Indeed, several GLS inhibitors have demonstrated efficacy in preclinical cancer models and some of them have entered clinical trials." (PMID 38067269, 2023). "Furthermore, BIS directly regulates metabolism by stabilizing hexokinase 2 mRNA and glutaminase in cancer cells." (PMID 37298584, 2023). "GLS1 is a cancer-specific glutaminase and catalyzes the glutamine conversion into α-ketoglutarate." (PMID 36820067, 2023). "However, GLS was upregulated in tumor cells derived from cancer compared with epithelial cells derived from normal samples." (PMID 36587392, 2023). "Lastly, pro-drugs, such as DRP104, target GLS-1 in tumors and cause CD8+ T cell-dependent tumor regression Such approaches could potentially unleash the immune cells in destroying cancer cells in the TME." (PMID 37274280, 2023). "Furthermore, mTORC1 not only regulates GDH, but also promotes glutamine uptake by cancer cells by positively regulating GLS through S6K1-dependent c-MYC regulation." (PMID 36959802, 2023). "MYC, SLC1A5, mTORC1, and glutaminase could be further utilized as a biomarker to recognize glutamine-addicted cancers." (PMID 37635935, 2023). "Additionally, glutaminase (GLS), an enzyme that converts glutamine to glutamate, is involved in cancer cell metabolism, growth, and proliferation and in certain cancers is regulated by BAG3." (PMID 36980278, 2023). "In malignancies of different cancer subtypes, glutaminase (GLS) transcripts are elevated." (PMID 37426676, 2023). "Transcription factor Myc activates glutaminase expression and glutamine metabolism in cancer cells." (PMID 37190313, 2023). "GLS is up-regulated in many cancers, and a recent study also showed that GLS depletion could inhibit CRC proliferation and migration through Nrf2 and an autophagy-dependent pathway." (PMID 37190215, 2023). "Future research should focus on determining whether the mechanism described in HCC is universal and also applies to other types of cancer; moreover, further work is needed to investigate the effects of simultaneous GLS silencing and GLS2 overexpression." (PMID 38067269, 2023). "Despite the developments in GLS inhibitors, notable setbacks in the development of pro-drugs greatly driven by the lack of selectivity and poor bioavailability causes some cancer cells to show resistance to glutaminase inhibitors." (PMID 36831355, 2023). "Furthermore, the expression levels of glutaminase and glutamine dehydrogenase were also increased in cancer cell lines after ARV infection." (PMID 36851737, 2023). "Some lines of evidence further reveal that CB-839, a glutaminase inhibitor, or cyst(e)inase might be used against cancer." (PMID 37525297, 2023). "Therefore, glutamine metabolism-related specific pathways have been ideal targets for developing anti-cancer drugs, with glutamine uptake inhibitors, glutamine antimetabolites, and glutaminase inhibitors being potential approaches." (PMID 36970537, 2023). "Several preclinical studies have indicated that a combination therapy with glutaminase inhibitors could provide a survival advantage to cancer patients." (PMID 37233659, 2023). "GLS has been reported to be a key enzyme in the Gln metabolism of cancer cells." (PMID 36151426, 2023). "Clinical trials of glutaminase inhibitor CB-839 (Telaglenastat) against various types of cancers." (PMID 36959802, 2023). "Based on previous findings, it was presumed that targeted glutaminase could inhibit cancer progression." (PMID 37946141, 2023). "Numerous types of cancers are characterized by increased glutamine consumption mainly by regulating the activity of glutamine-related enzymes such as glutamine synthetase (GS) and glutaminase (GLS)." (PMID 36970537, 2023).